EGFR (epidermal growth factor receptor)
Diseases named in the same sentence as EGFR in open-access papers (continued):
Sharing a sentence is not in itself a finding about the gene and the disease.
lung adenocarcinoma (continued). "If we can recover the directly affected, higher interconnected genes of a disease, we can get rid of those selected diseases (hypopharyngeal cancer and EGFR‐mutated lung adenocarcinoma)." (PMID 38783639, 2024). "It aims to explore clinical, molecular, and immune microenvironment characteristics associated with PD‐L1 expression in EGFR/ALK wild‐type lung adenocarcinoma patients eligible for ICI therapy." (PMID 38396367, 2024). "Univariate and Multivariate analyses for recurrence free survival among the patients with EGFR-mutated lung adenocarcinoma." (PMID 39281386, 2024). "In this research, we aimed to look into common DEGs (differentially expressed genes), hub genes, various gene regulatory networks, and therapeutic molecule for hypopharyngeal cancer and EGFR‐mutated lung adenocarcinoma using bioinformatics technology." (PMID 38783639, 2024). "Identification of distinct mutations, such as those in EGFR observed in lung adenocarcinoma, and of their correlation with heightened bone metastasis presents precise targets for therapeutic measures and prognostic evaluations." (PMID 38791037, 2024). "If some related illnesses are found with hypopharyngeal cancer and EGFR‐mutated lung adenocarcinoma, then future research in this area aims to create a single generic drug to treat some related illnesses, offering a fresh perspective." (PMID 38783639, 2024). "Pathological analysis of bronchoalveolar lavage fluid sediment confirmed lung adenocarcinoma, and genetic testing of blood identified an EGFR E19 mutation." (PMID 39334060, 2024). "Approximately 45-50% of Asian patients with lung adenocarcinoma have EGFR mutations and the prevalence of ALK mutations is around 7%." (PMID 39850198, 2024). "We report a case of a 62-year-old male with stage IV lung adenocarcinoma and EGFR L858R mutation who was treated with osimertinib at a dose of 80 mg/day as first-line therapy." (PMID 38895622, 2024). "The Oceania lung adenocarcinoma patients, which only included data from Australia, had the lowest EGFR mutation frequency at 12%." (PMID 38886907, 2024). "Epidermal growth factor receptor (EGFR) gene mutations are prevalent in about 50% of lung adenocarcinoma patients." (PMID 39130636, 2024). "The protocol presented here describes how to model acquired resistance to the 3rd-generation EGFR-TKI osimertinib in EGFR-mutated lung adenocarcinoma cells." (PMID 39369385, 2024). "Hypopharyngeal cancer and EGFR‐mutated lung adenocarcinoma can be associated with each other directly or indirectly." (PMID 38783639, 2024). "Researchers have discovered epidermal growth factor receptor (EGFR) mutations in patients with lung adenocarcinoma, which have been linked to their response to EGFR inhibitors." (PMID 38338729, 2024). "Another study conducted revealed that EGFR mutations were associated with a higher incidence of bone metastasis in lung adenocarcinoma." (PMID 38791037, 2024). "EGFR-targeted drugs target tyrosine kinase receptors that are frequently overactivated in lung adenocarcinoma cells due to genetic mutations, promoting tumor growth and survival." (PMID 38965505, 2024). "Common EGFR mutations were detected in 96 of 221 patients with lung adenocarcinoma (43.4%), and uncommon EGFR mutations were detected in 9 of 221 patients (4.1%)." (PMID 39281386, 2024). "The results showed that pleural fluid CEA was an independent predictor of EGFR mutation in patients with lung adenocarcinoma with MPE (OR: 1.024, 95% CI: 1.011–1.037, P < 0.001)." (PMID 37775991, 2024). "By altering the interaction between tumor cells and the microenvironment, as well as affecting the invasiveness and migratory abilities of tumor cells, EGFR mutations can modify the metastatic patterns of lung adenocarcinoma." (PMID 39193383, 2024).
lung adenocarcinoma (continued). "To further investigate the antitumor efficacy of WntSI in patients with NSCLC, we established a patient‐derived xenograft (PDX) model of lung adenocarcinoma harboring EGFR mutation and MET amplification in NOD/SCID mice." (PMID 38867713, 2024). "In particular, EGFR-positive mutations play an important role in brain metastasis in lung adenocarcinoma." (PMID 38605303, 2024). "The most common are EGFR exon 20 insertions, which represent 2.5% of all lung adenocarcinomas and 6% of EGFR-mutations in NSCLC." (PMID 38347643, 2024). "Epidermal growth factor receptor (EGFR) mutations are major genetic variants reported in lung adenocarcinomas, with reported incidences of approximately 50% in Asians and 10–15% in Caucasians." (PMID 39280252, 2024). "In this study, we aimed to directly distinguish between EGFR (+) and EGFR (-) and then differentiate between two common subtypes of EGFR mutations, ex19Del and L858R, using DL and ML analysis of primary lung adenocarcinoma." (PMID 39619439, 2024). "PD-L1 positivity is an independent risk factor for RFS in patients with EGFR-mutated lung adenocarcinoma." (PMID 39281386, 2024). "This study aimed to characterize the clinical and molecular features of EGFR-mutated lung adenocarcinomas and determine the prognostic significance associated with high PD-L1 expression." (PMID 39509381, 2024). "Comparison of the predictive efficacy of pleural fluid CEA, serum CEA and pleural fluid CEA/serum CEA combined with pleural fluid CEA for EGFR mutations in patients with lung adenocarcinoma with MPE." (PMID 37775991, 2024). "Previous studies have also shown that the co-occurrence of p16/CDKN2A homozygous deletion and activated EGFR mutation in patients with lung adenocarcinoma results in decreased responsiveness to EGFR-TKIs." (PMID 39323996, 2024). "Mutations in the epidermal growth factor receptor (EGFR) gene account for about 27% of lung adenocarcinoma (LUAD) cases." (PMID 40994652, 2024). "In Asian countries, and among Asian populations, EGFR mutations can be detected in more than 50% of patients with lung adenocarcinoma." (PMID 38347643, 2024). "We summarize the diagnosis and treatment of a female patient with EGFR 21L858R mutation combined with Her-2 overexpression in advanced lung adenocarcinoma, and analyze the effect of c in her treatment process." (PMID 39726714, 2024). "We routinely conducted EGFR mutation assessments and evaluated the PD-L1 status in all patients with surgically resected lung adenocarcinoma." (PMID 39281386, 2024). "Four months after the skin rash worsened, the patient was diagnosed with epidermal growth factor receptor mutation-positive lung adenocarcinoma via bronchoscopy." (PMID 39703278, 2024). "This case underscores the challenges in treating bone metastasis in EGFR exon 19-mutated lung adenocarcinoma with osimertinib." (PMID 39108772, 2024). "Despite experiencing a higher recurrence rate, patients with EGFR-mutated lung adenocarcinoma exhibited relatively better overall survival." (PMID 39281386, 2024). "In summary, our study examined the effectiveness of combining EGFR-TKIs and local radiation for EGFRm lung adenocarcinoma, focusing on pneumonitis risk." (PMID 39772073, 2024). "Due to the small sample sizes for individual gene mutations, we explored the impact of pathway mutations on immunotherapy outcomes in EGFR/ALK wild‐type lung adenocarcinoma patients." (PMID 38396367, 2024). "For example, a 50-year-old man diagnosed with lung adenocarcinoma with EGFR T790M and EGFR E746_A750del mutations experienced disease progression after treatment with osimertinib." (PMID 39529955, 2024). "For EGFR-mutated lung adenocarcinoma patients with a higher number of brain metastases, the timely addition of cranial radiotherapy has been shown to benefit these patients." (PMID 38515096, 2024).
lung adenocarcinoma (continued). "We report the case of a 63-year-old Chinese woman diagnosed with synchronous lung adenocarcinoma harboring an EGFR exon 21 far-loop insertion mutation and clear cell renal cell carcinoma (ccRCC)." (PMID 39743996, 2024). "For instance, a male patient with lung adenocarcinoma underwent genetic testing after osimertinib treatment failure, which revealed co-mutations of EGFR T790M/19del and BRAF V600E." (PMID 39135785, 2024). "Activating mutations in the epidermal growth factor receptor (EGFR) occur in 15-20% of lung adenocarcinomas in Western populations." (PMID 38182677, 2024). "PD-L1 positivity emerged as an independent risk factor for RFS in patients with EGFR-mutant resected lung adenocarcinoma." (PMID 39281386, 2024). "Further studies are needed to better understand the molecular mechanisms underlying the emergence of DTP cells in EGFR-mutated lung adenocarcinoma and their role in treatment resistance." (PMID 39001552, 2024). "In this study, we report a case of a lung adenocarcinoma family lineage linked to a germline EGFR T790M mutation." (PMID 39160638, 2024). "High PD-L1 expression was more commonly found in lung adenocarcinomas with uncommon and complex EGFR mutations." (PMID 39509381, 2024). "To investigate any correlation between patients with rs822336 genotypes and EGFR mutation status in lung adenocarcinoma patients, we utilized data from TCGA, specifically selecting the Lung Adenocarcinoma Firehose Legacy dataset." (PMID 38528526, 2024). "We found 605 identical DEGs for hypopharyngeal cancer (GSE212398) and 1062 identical DEGs for EGFR‐mutated lung adenocarcinoma (GSE198672) by using the R programming language." (PMID 38783639, 2024). "This retrospective study included patients with advanced-stage lung adenocarcinoma who were confirmed to have EGFR T790M mutation and to have received osimertinib from January 2020 to February 2021 at Samsung Medical Center." (PMID 39298415, 2024). "A retrospective dual-center study was conducted involving patients with advanced lung adenocarcinoma and EGFR mutations who developed resistance to EGFR-TKIs between January 2017 and December 2022." (PMID 38402169, 2024). "The risk of lung adenocarcinoma in patients with EGFR mutation-positive pulmonary nodules carrying the DD genotype (OR = 0.312, 95% CI, 0.101–0.968, p = 0.044) is lower than that in patients carrying genotype II." (PMID 37371643, 2023). "There are some studies on the pathological analysis of EGFR mutations in patients with early-stage lung adenocarcinoma." (PMID 36766495, 2023). "The clinical characteristics of lung adenocarcinoma patients are important variables in evaluating EGFR mutation status." (PMID 37014500, 2023). "Epidermal growth factor receptor (EGFR)-activating mutations represent the most frequent targetable alteration with a prevalence of nearly 20% in Caucasians with lung adenocarcinomas." (PMID 37915579, 2023). "Other studies have reached the same conclusion, showing that targeted therapy is significantly more effective than conventional regimens in the postoperative adjuvant treatment of patients with early-stage lung adenocarcinoma with EGFR gene mutations." (PMID 37910672, 2023). "This study aimed to analyze the postoperative prognosis and clinicopathological characteristics associated with EGFR mutations in operable lung adenocarcinoma." (PMID 36766495, 2023). "There is increasing interest in the relationship between EGFR mutations and resectable lung adenocarcinoma." (PMID 36766495, 2023). "In conclusion, radiomic features extracted from the peritumoral region can add extra value in predicting the EGFR mutation status of lung adenocarcinoma patients, with the optimal peritumoral range of 4 mm." (PMID 37749461, 2023). "Approximately 40–50% and 10–15% of patients with lung adenocarcinoma in Asian and Western countries, respectively, harbor an active mutation in the gene encoding epidermal growth factor receptor (EGFR)." (PMID 36831438, 2023).
lung adenocarcinoma (continued). "Gefitinib and erlotinib, first-generation EGFR-TKIs, were investigated for their efficacy for the treatment of lung adenocarcinomas with the G719X, L861Q, and S768I mutations in a multicenter study from Taiwan." (PMID 37366888, 2023). "Our results demonstrate that 18F-FDG PET/CT imaging can be an effective non-invasive approach to predict EGFR mutations in lung adenocarcinoma patients." (PMID 36983578, 2023). "Studies on applying 18F-FDG PET/CT DL in predicting EGFR mutations in patients with lung adenocarcinoma." (PMID 38094613, 2023). "The biological activities of MUC21, including its involvement in the progression of EGFR-mutated lung adenocarcinomas or its ability to confer resistance to apoptosis, are thought to rely on specific glycosylation patterns." (PMID 37858248, 2023). "In this report, we present the treatment course of 3 patients with advanced EGFR 19 deletion-mutated lung adenocarcinoma with bone metastases who were treated with osimertinib." (PMID 37653755, 2023). "RBP1 is highly expressed in lung adenocarcinoma and mediates cell proliferation and differentiation by up-regulating Akt/Erk/ EGFR pathway, which is associated with increased tumor grade." (PMID 36970364, 2023). "In lung adenocarcinoma, one of the most frequently mutated oncogenes is EGFR, and the mutated form offers a feasible therapeutic target." (PMID 36754910, 2023). "Epidermal growth factor receptor (EGFR)-mutated (mt) lung adenocarcinoma (LA) is refractory to immune checkpoint inhibitors (ICIs)." (PMID 36991099, 2023). "We also found that the ACE1 rs4646994 DD genotype frequency was inversely correlated with the risk of EGFR mutation in lung adenocarcinoma patients." (PMID 37371643, 2023). "A total of 111 lung adenocarcinoma patients with EGFR mutations, who received thoracic radiotherapy, were included in this retrospective study." (PMID 36070068, 2023). "We report a case of a patient with advanced lung adenocarcinoma with EGFR-T790M and C797s cis mutations who were treated with lazertinib and achieved satisfactory efficacy without serious side effects." (PMID 36698414, 2023). "We examined the distributions of 22 immune cell types and the responses to PD-1/PD-L1 inhibitors according to EGFR mutation profile, in three independent datasets of lung adenocarcinoma (LUAD)." (PMID 37033978, 2023). "In this multicenter, retrospective cohort study, we found that patients treated with first-line afatinib for advanced lung adenocarcinoma harboring susceptible EGFR mutations benefited from add-on LCT, leading to better PFS and OS." (PMID 37046679, 2023). "Patients with lung adenocarcinoma (LUAD) patients carrying EGFR mutations are often treated with EGFR-tyrosine kinase inhibitors (EGFR-TKIs), but sensitivity to the therapy varies." (PMID 37268635, 2023). "In conclusion, in this multicenter, retrospective cohort study, LCT was found to prolong PFS and OS in patients with advanced lung adenocarcinomas, who were harboring susceptible EGFR mutations and treated with first-line afatinib." (PMID 37046679, 2023). "Lung adenocarcinoma cell lines with EGFR mutations are also known to recruit regulatory T cells (Tregs) as a result of high C-C motif chemokine 22 (CCL22) expression, creating a suppressive tumor-immune microenvironment." (PMID 36672698, 2023). "Our study is one of the largest-scale multicenter retrospective studies examining EGFR-TKI plus LCT for the treatment of advanced lung adenocarcinoma patients harboring susceptible EGFR mutations." (PMID 37046679, 2023). "We investigated the ability of different modeling approaches to predict EGFR mutational status in lung adenocarcinoma resections (see “Methods” for details)." (PMID 36927889, 2023).
lung adenocarcinoma (continued). "In the present study, 5 out of 31 texture indices were significantly different between the mutated EGFR and wild-type EGFR groups in patients with newly diagnosed lung adenocarcinoma." (PMID 37185611, 2023). "Then, we aimed to enhance the understanding of radiomic features associated with KRAS and EGFR mutations in lung adenocarcinoma and to evaluate the effectiveness of the features in accurately classifying mutations." (PMID 37508774, 2023). "Mutated EGFR lung adenocarcinoma patients with ever TKI treatment had significantly better survival than with other treatments." (PMID 37833769, 2023). "Here, we report a patient with advanced lung adenocarcinoma harboring an EGFR exon 20 insertion mutation (NM_005228: exon 20: c.2316_2321dup: p.773_774dup)." (PMID 36817153, 2023). "EGFR mutation-positive advanced NSCLC accounts for 10%–15% of lung adenocarcinomas among Westerners and even higher among Asians." (PMID 37194236, 2023). "We report for the first time 2 Chinese patients diagnosed with advanced lung adenocarcinoma with EGFR ex20ins mutations after analysis of the αC-helix sequence by next-generation sequencing." (PMID 38206746, 2023). "A large-scale clinical study showed that gefitinib provided a striking antitumor activity for lung adenocarcinoma with EGFR-activating mutations." (PMID 37371816, 2023). "It has been confirmed that the continuous activation of epidermal growth factor receptor (EGFR) tyrosine kinase domain in tumor tissues is caused by the mutation of EGFR in lung adenocarcinoma." (PMID 37143947, 2023). "Most research on lung adenocarcinoma during the past ten years has concentrated on mutations of the epidermal growth factor receptor (EGFR)." (PMID 36900362, 2023). "Various studies have shown that certain tumor architectural patterns and cytological features are correlated with EGFR mutated tumors in lung adenocarcinoma." (PMID 36927889, 2023). "EXOs derived from patients with EGFR-positive lung adenocarcinoma caused, in recipient cells, vimentin overexpression, extracellular matrix degradation, and activation of PI3K/AKT/mTOR, a well-known pathway involved in the EMT process." (PMID 37296932, 2023). "In this study, we examined the protein expression profiles of early and epidermal growth factor receptor (EGFR) mutation‐positive lung adenocarcinomas." (PMID 37004157, 2023). "Most importantly, advanced NSCLC patients who harbor epidermal growth factor receptor (EGFR) mutations, which were found in about half of the advanced lung adenocarcinoma cases in Asians, can be treated with EGFR-tyrosine kinase inhibitor (TKI)." (PMID 36900237, 2023). "Third-generation epidermal growth factor receptor (EGFR) tyrosine kinase inhibitors were recently reported to be effective as adjuvant therapy for resected lung adenocarcinoma (ADC) harbouring common EGFR mutations." (PMID 37930012, 2023). "According to current treatment guidelines for lung adenocarcinoma, detection of EGFR mutations is the first recommendation for patients with advanced or inoperable lung adenocarcinoma." (PMID 36766495, 2023). "The potential for sequential use of combinatorial therapy of osimertinib and cabozantinib has also been demonstrated in a case study where a patient with EGFR-mutated lung adenocarcinoma acquired four MET mutations upon crizotinib treatment." (PMID 36698189, 2023). "We also found that EGFR-TKI therapy was associated with hemorrhage in BMs from lung adenocarcinomas, particularly when combined with radiation therapy." (PMID 36765577, 2023).